SMAD4 (SMAD family member 4)
Diseases named in the same sentence as SMAD4 in open-access papers (continued):
Sharing a sentence is not in itself a finding about the gene and the disease.
tumor (continued). "However, the loss of SMAD4 can facilitate tumor progression initiated by other oncogenic factors." (PMID 39459634, 2024). "In addition, transcription factor analysis demonstrated that the transcription factor SMAD4 might be involved in these gene expression changes often associated with EMT in tumor cells." (PMID 38334007, 2024). "Furthermore, sh-NC and sh-Smad4 Hepa1-6 cells were inoculated subcutaneously in nude mice and Smad4 deficiency in Hepa1-6 cells didn't inhibit tumor growth compared with the sh-NC group, indicating that the anti-tumor effects of Smad4 mainly depended on the host's T cells, but not tumor cells." (PMID 39346534, 2024). "Our results showed that SMAD4 expression was associated with tumor differentiation (OR = 0.359, 95% CI: 0.238–0.543, P = .000), lymph node metastasis (OR = 0.469, 95% CI: 0.04–0.725, P = .001), and tumor node metastasis (TNM) stage (OR = 0.238, 95% CI: 0.156–0.362, P = .000) in NSCLC patients." (PMID 37478236, 2023). "Additionally, there is the possibility of sampling error in tumor biopsies, which could lead to mischaracterizations of SMAD4 mutational status or GATA6 mRNA expression." (PMID 38002058, 2023). "Finally, we reported inhibition of TGFβ/SMAD pathway (by TGFβ inhibitor LY2157299 or SMAD4 siRNA) could reverse the tumor‐promoting effects caused by CKS2." (PMID 36284444, 2023). "Clinical implications of loss of RUNX3 and/or SMAD4 expression in the tumor epithelial compartment may be used to identify stage II patients in need of adjuvant chemotherapy, or patients with T1-3N1 tumors eligible for extended chemotherapy compared to the three month standard for this risk group." (PMID 36900240, 2023). "SMAD4 was also found to be survival-related in several studies and this study, whether there are common pathways involved in SMAD4 mutation and elevated tumor biomarkers needs future experiments to clarify." (PMID 35180847, 2022). "Nevertheless, human PDACs are highly resistant to anti‐PD1 or anti‐cytotoxic T lymphocyte‐associated antigen‐4 (CTLA4)‐based immunotherapy except a few microsatellite‐unstable cases, suggesting that SMAD4 loss alone could be insufficient to promote tumor response to checkpoint blockade." (PMID 35064757, 2022). "However, in a model in which the deletion of phosphatase and tensin homolog deleted on chromosome ten (Pten) and SMAD family member 4 (Smad4) from airway epithelial cells results in the development of spontaneous tumors, tumor incidence was increased in mice deficient for IL-17A." (PMID 35883573, 2022). "Finally, we show that in HPV-positive cell lines SMAD4-loss sensitizes cells to DNA-damaging agents, such as cisplatin, suggesting that SMAD4-deficient HPV tumours may be preferentially susceptible to similar treatments." (PMID 35144669, 2022).
tumor (continued). "In addition, acquired SMAD4 mutations enhance the chemoresistance profile of epithelial OvCA cells, representing a mechanism in which exchange of tumor-derived exosomes perpetuates an EMT phenotype, leading to the development of subpopulations of platinum-refractory tumor cells." (PMID 34768926, 2021). "However, loss of Smad4 converts BMP signalling from a tumour suppressor to a metastasis promoter." (PMID 33673710, 2021). "Tumor-initiating genetic events may influence subsequent evolutionary trajectories and may lead to parallel evolution, in which the fitness state of specific subclones depends on mutations in the same gene (SMAD4) or pathway (e.g., TGFβ signaling pathway)." (PMID 34749812, 2021). "Consequently, the loss of SMAD4 tumour suppressive function may contribute to pancreatic oncogenesis through the TFG-β canonical pathway." (PMID 33371431, 2020). "Interestingly, in ex vivo cultures derived from PDX, the cell subpopulation displaying heterozygous SMAD4 loss by deletion or reduced expression outcompeted cells with wildtype SMAD4 genotype from the parental tumor, suggesting a survival advantage of Smad4-deficient cells." (PMID 32714605, 2020). "Taken together, these studies suggest that different mechanisms contribute to inactivate SMAD4 and possibly the tumor suppressive arm of the TGFβ pathway, both in eCCA, involving SMAD4 inactivating point mutations, and in iCCA, involving a transcriptional down-regulation of SMAD4." (PMID 31450767, 2019). "Interestingly, in human CRC samples, CCL15 (the human orthologue to murine CCL9) expression appears to be inversely correlated with SMAD4 expression, and increased tumor CCL15 expression is associated with a three-fold increase in CCR1+ immune cell infiltration." (PMID 33834163, 2019). "Notably, CSCs/CICs bearing a somatic mutation in the CRC-associated “driver” gene SMAD4, could elicit antigen-specific T cell responses directed to both stemness and differentiated components of tumor." (PMID 31758404, 2019). "Finally, it should be noted that inactivation of BMP and Activin signaling are also implicated in cancer development, hence the tumor suppressor function of Smad4 may also involve a requirement in mediating signaling from these receptors." (PMID 31480737, 2019). "Moreover, SMAD4 was associated with tumor invasion, metastasis and prognosis in different cancers." (PMID 28199217, 2017). "SMAD4 activation under different conditions could lead to apoptosis or growth arrest in the G1 phase of the cell cycle, which are responses associated mainly with tumor development." (PMID 28199217, 2017). "Similarly, we found significantly more functional interactions among the kinases identified as dependencies associated with mutation of the tumor suppressor SMAD4, a member of the TGF-β pathway that is frequently mutated or homozygously deleted in colorectal, pancreatic, and esophageal cancers." (PMID 26947069, 2016). "Whereas, based on most of SMAD4 inactivated in later stage of PDACs, further works should focus on whether miR-301a-3p expression is associated with SMAD4 expression in terms of different tumor stages." (PMID 26019136, 2015). "As an approach towards modelling the cytokine environment in tumor tissues we here address effects of TNFα, a prominent inflammatory cytokine produced by tumor infiltrating macrophages, on laminin-332 expression in Smad4-positive and Smad4-deficient tumor cells." (PMID 20307265, 2010).
tumor (continued). "As an approach towards modelling the microenvironment in tumor tissues we here wished to address effects of TNFα, a prominent inflammatory cytokine produced by tumor infiltrating macrophages, on laminin-332 expression of Smad4-positive and Smad4-deficient tumor cells." (PMID 20307265, 2010). "We have thus unraveled a novel molecular mechanism of how loss of the tumor suppressor Smad4 may promote the carcinogenic process in vivo, where tumor cells interact with stromal cell types and respond to inflammatory cytokines like TNFα expressed by macrophages at the tumor host interface." (PMID 20307265, 2010). "Loss of Smad4 may lead to uncoupled induction of laminin-γ2 in response to TNFα and may therefore represent one of the mechanisms which underlie accumulation of laminin-γ2 at the invasive margin of a tumor." (PMID 20307265, 2010). "Conversely, our own observation, according to which more advanced lesions of the Smad4+/E6sad mouse model show complete loss of Smad4 expression, is indicative of an additional role for the complete loss of Smad4 function in the epithelial compartment at later tumor progression stages." (PMID 19014666, 2008). "We and others showed that mice carrying targeted Smad4 mutations develop gastrointestinal (GI) polyps with initial retention of the wild-type Smad4 allele; complete functional loss only occurs at later stages of tumor progression within the epithelial compartment." (PMID 19014666, 2008). "Our study demonstrates that SMAD4 loss enables NFATc1 to drive STAT3 expression, creating a dependency that fuels tumor progression." (PMID 40856537, 2026). "Here, we identify SMAD4 as a critical regulator of three-dimensional (3D) genome organization in LUSC and uncover a mechanistic link between tumor suppressor loss and oncogenic transcriptional activation." (PMID 42189071, 2026). "Loss of SMAD4 leads to enhanced H3K27ac deposition, aberrant SOX2 activation, and increased LUSC tumor cell proliferation." (PMID 42189071, 2026). "In conclusion, this study identifies the SMAD4–NFATc1–STAT3 axis as a critical mediator of oncogenesis in SMAD4-deficient PDAC, offering novel insights into how the loss of a tumor suppressor rewires transcriptional networks to drive tumor progression." (PMID 40856537, 2026). "Loss of SMAD4 disrupts TGF‐β signaling, and has been associated with tumor progression, metastasis, and reduced chemosensitivity." (PMID 41562159, 2026). "This cell viability-based screen identified 142 compounds that demonstrated >2-fold higher anti-tumor activity in SMAD4-KD cells compared to their WT counterparts." (PMID 40856537, 2026). "As experimental inactivation of 14-3-3σ abolished these tumor-suppressive functions of SMAD4, 14-3-3σ mediates these effects of SMAD4." (PMID 42014683, 2026). "Regressive mutations in KRAS and SMAD4, as well as specific ERBB2 point mutations, have been shown to influence tumor growth kinetics, metastatic behavior, and responsiveness to targeted or cytotoxic agents." (PMID 41492104, 2026). "SMAD4 LOF also blocked differentiation during tumour progression in an orthotopic organoid transplantation model mimicking an intestinal adenoma-carcinoma transition." (PMID 40348815, 2025). "CDKN2A gene codes for cell cycle inhibitors, p16 signalling and SMAD4, which act as transducers of the transforming growth factor beta (TGF-β) signalling pathway, and are two commonly mutated tumor suppressors found in about 20% of PDAC cases." (PMID 40230862, 2025). "In support of a liver-specific cytostatic response and shared fibrogenic response, Smad4 reactivation reduced the proportion of Ki67+ tumor cells only in the liver, while both the liver and lungs exhibited increases in α-SMA levels." (PMID 40999053, 2025).
tumor (continued). "Leveraging the mKate2 reporter in our model, we used fluorescence-activated cell sorting (FACS) to isolate tumor (mKate2+) cells 7 and 14 days after Dox withdrawal, which allowed for assessment of Smad4 output kinetics." (PMID 40999053, 2025). "TGF-β1 increased tumor sensitivity to the ferroptosis inducer RAS-selective lethal 3 (RSL3) via the SMAD4-GPX4 axis in SMAD4-positive organoids and pancreas xenograft models." (PMID 39939803, 2025). "The TGF-β signaling pathway exhibits pleiotropic behavior, functioning as a tumor-suppressor in normal cells but transitioning to a tumor-promoting pathway under specific scenarios, one of which is the inactivation of SMAD4." (PMID 40338154, 2025). "In the TGF-Beta pathway, SMAD2 mutations were more frequent in H/L patients, while SMAD4 mutations were more common in NHW patients, indicating potential differences in tumor suppressor pathway disruption." (PMID 40869017, 2025). "Our findings indicated that early-stage OSCC tissues exhibit higher E-cadherin and Smad4 expression, along with lower N-cadherin and Vimentin levels, suggesting their utility as early indicators of tumor progression." (PMID 40507242, 2025). "Many of the tumour suppressive effects of TGF-β are mediated by SMAD4, while the oncogenic pathways are mostly SMAD4-independent." (PMID 40427100, 2025). "Previous studies showed that SMAD4 plays a tumor suppressor role, and SMAD4 overexpression suppresses HCC cell invasion, proliferation, and migration." (PMID 38407690, 2025). "To test this, we performed ATAC-seq (assay for transposase-accessible chromatin using sequencing) on FACS-isolated tumor cells from the pancreas, liver and lungs ± Smad4 restoration." (PMID 40999053, 2025). "The higher immunogenicity of TC was accompanied by the more profound expression of STAT6 and SMAD4 in tumor cells." (PMID 39936166, 2025). "Smad4, a critical TGF-β signaling component, restores tumor immunogenicity in Smad4-deficient cells, driving cDC1s activation and antigen uptake." (PMID 40924040, 2025). "As anticipated, we observed that the inhibition of tumor growth induced by overexpression of AMDHD1 was reversed after SMAD4 depletion." (PMID 39143229, 2025). "SMAD4 inactivating mutations are present in approximately 50% of PDAC patients and lead to impaired TGF‐β pathway signaling and loss of its tumor suppressive functions." (PMID 40739706, 2025). "The remaining four SMAD4 wild‐type primary PDTs harbored KRASG12D (PDT2,5), KRASG12V (PDT4) or exon 4 KRASA146T (PDT3) mutations and exhibited tumor‐suppressive effects upon TGF‐β1 treatment." (PMID 40066744, 2025). "In this study, we also found that TC demonstrated much higher expression of SMAD4 in tumor cells compared to TA." (PMID 39936166, 2025). "The canonical TGF-β/SMAD4 signaling pathway plays a tumor suppressive role at early stages, mainly by inducing G0/G1 cell cycle arrest and apoptosis." (PMID 40224178, 2025). "The tumor suppressor SMAD4 (Mothers against decapentaplegic homolog 4) is inactivated in approximately 50%-60% of PDAC cases, disrupting the activation of the DLG1/YAP1 pathway." (PMID 39897038, 2025). "This transition is usually associated with mutations or deletions in TGF-β receptors (e.g., TGFβRII) or Smad4, leading to tumor cell migration and invasion, dysregulation of TME, and promotion of tumor immune escape and angiogenesis." (PMID 40699666, 2025).
tumor (continued). "Strikingly, the response to Smad4 restoration was different in each of the three organs; tumor burden was unchanged in the pancreas, decreased in the liver and increased in the lungs." (PMID 40999053, 2025). "Conversely, the loss of Smad4 was associated with increased EMT marker expression and enhanced tumor-cell migration and proliferation." (PMID 40507242, 2025). "We performed ATAC-seq on the Smad4-off primary tumor-derived cell lines used to generate liver and lung metastases and on matched cell lines derived from the respective metastatic sites." (PMID 40999053, 2025). "The lung-derived but not liver-derived cells had a blunted cytostatic response to TGFβ in vitro relative to their matching primary tumor cells, indicating that the lung favors a cell-intrinsic state that is resistant to the tumor-suppressive effects of SMAD4." (PMID 40999053, 2025). "During cancer progression, SMAD4 inactivation shifts TGFβ’s activity from tumor-suppressive to tumor-promoting by impairing its ability to trigger cell-cycle arrest and EMT-coupled apoptosis." (PMID 40999053, 2025). "Taken together, we report that METTL3, an oncogene regulates the expression of SMAD4, a tumor-suppressor via miR-146a-5p, thus unveiling a novel regulatory axis of METTL3/miR-146a-5p/SMAD4 in OSCC, which can potentially have therapeutic implications." (PMID 40338154, 2025). "This genetic strategy allows for tumor development in the setting of Smad4 depletion (through Dox administration) and subsequent restoration of Smad4 expression at physiological levels from its endogenous locus (through Dox withdrawal)." (PMID 40999053, 2025). "After 4–6 weeks, which allowed for tumor formation under Smad4-depleted conditions (+Dox = Smad4 off), Smad4 expression was restored by Dox withdrawal (−Dox = Smad4 on) in a randomly selected half of each cohort and tumor burden was assessed 30 days later." (PMID 40999053, 2025). "Collectively, these results underscore the tumor-suppressive role of SMAD4 in OSCC cells by regulating cell proliferation, apoptosis, migration, and invasion." (PMID 40338154, 2025). "While tumor‐suppressive consequences were observed in most of the primary SMAD4 wild‐type PDTs, metastatic lines were less sensitive, and the presence of an atypical KRASQ22K mutation rendered PDT1 insensitive to the inhibitory effects of TGF‐β1." (PMID 40066744, 2025). "SMAD4 is a tumor suppressor gene and acts as a mediator of the TGF-β signaling pathway, and SMAD4 mutations contribute to tumor progression by disrupting cellular differentiation and proliferation." (PMID 41075061, 2025).